ENSG00000273966
Gene: Miscellaneous RNA gene on chromosome Y (17,568,962 to 17,569,051, reverse strand). Ensembl gene ENSG00000273966.
Gene Ontology:
Biological process: chromatin remodeling